TWIST1 (twist family bHLH transcription factor 1)
Diseases named in the same sentence as TWIST1 in open-access papers (continued):
Sharing a sentence is not in itself a finding about the gene and the disease.
glioblastoma (34 papers, 2010 to 2025). The most malignant astrocytic tumor (WHO grade IV). "TWIST1 (TW) is a pro-oncogenic basic helix-loop-helix (bHLH) transcription factor and promotes the hallmark features of malignancy (e.g., cell invasion, cancer cell stemness, and treatment resistance), which contribute to poor prognoses of glioblastoma (GBM)." (PMID 37507199, 2023). "Interestingly, USP18 associates with TWIST1 and mediates the stabilization of TWIST1, thereby leading to glioblastoma cell migration and invasion." (PMID 32957626, 2020). "There is a direct correlation between the expression of SOX2 and TWIST1 in glioblastoma cells, suggesting their interaction to maintain stemness and EMT ability." (PMID 36553636, 2022). "Initially, we examined the expression levels of mesenchymal markers (vimentin, Twist1, Snail and Slug) in U251 glioblastoma cells via overexpression or depletion of Bcl-w with RNA interference." (PMID 23826359, 2013). "The expression of Sox2 has been shown to correlate with that of Twist1 in human glioblastoma cells, although direct proof that Sox2 regulates the expression of Twist1 is lacking." (PMID 23815808, 2013). "Bcl-w promotes the mesenchymal traits of glioblastoma cells by inducing vimentin expression via activation of transcription factors, β-catenin, Twist1 and Snail in glioblastoma U251 cells." (PMID 23826359, 2013). "Over expression of Sox2 and Twist1 in glioblastoma enhances tumor cell invasion and metastasis, thus supporting roles for Twist1 and Sox2 in glial tumorigenesis and progression." (PMID 22184289, 2011). "Moreover, dual NR4A1/NR4A2 regulation of TWIST1 in glioblastoma cells has also recently been reported using a similar approach." (PMID 40332813, 2025). "Twist1 was shown to modulate the actin cytoskeleton in human glioblastoma." (PMID 36900319, 2023). "In glioblastoma (GBM), a subset of tumor ECs, via a Twist1/SATB1-mediated sequential transcriptional activation mechanism, produces osteopontin to promote immunosuppressive macrophage (Mφ) phenotypes that inhibit T cell infiltration and activation." (PMID 39337337, 2024). "Here, we demonstrate that JICD1 enhances the invasive phenotypes of glioblastoma cells by transcriptionally activating epithelial-to-mesenchymal transition (EMT)-related genes, especially TWIST1." (PMID 38092725, 2023). "Zhx1 promoted the proliferation, migration, and invasion of glioblastoma cells and cholangiocarcinoma cells by activating the transcription of the EMT genes Snail2 and Twist1 or enhancing the Egr1 expression, respectively." (PMID 37452012, 2023). "Silencing FGFR1 or FOXM1 downregulated genes involved in mesenchymal transition such as GLI2, TWIST1, and ZEB1 in glioblastoma stem-like cells." (PMID 30167084, 2018). "qRT-PCR showed significant upregulation of mesenchymal glioblastoma markers (>100-fold ZEB2; >10-fold TWIST1; FN1, <10-fold VIM; ZEB1; *p < 0.01) in KW10 cells as compared to MTA10 cells." (PMID 28744448, 2017). "Twist1 is reported to be a master regulator of EMT and metastasis in breast, gastric, hepatocellular, prostate, and brain cancers including glioblastoma." (PMID 22184289, 2011). "To determine the role of EMP3 on EMT in glioblastoma, we first performed a correlation analysis of gene expression, which showed that EMP3 was positively correlated with VIM, FOS, SNAI2 and TWIST1 (p < 0.001, R: VIM: 0.754, FOS:0.382, SNAI2: 0.498, TWIST1: 0.605)." (PMID 38229014, 2024). "This partial EMT phenotype is known for more malignant behavior of cancer cells, consistent with the results found in glioblastoma, where TWIST1 did not generate an E- to N-cadherin “switch” in GBM cell lines." (PMID 35152264, 2022). "We observed that the expression of apoptosis-related factors (BIM, BAX and cleaved CASPASE3) and an invasion-related factor (E-CADHERIN) were higher, while the expression of related invasion factors (TWIST1, SNAIL and MMP9) were lower in glioblastoma cells with HDAC1-shRNA infection." (PMID 28624794, 2017).
glioblastoma (continued). "The association of transcription factors, Sox2 (responsible for stemness) and Twist1 (responsible for EMT) thus provides a platform to correlate the stem cell pathway with EMT pathway, which can be further studied to address potential targets for glioblastoma cure." (PMID 22184289, 2011).
cervical cancer (31 papers, 2011 to 2026). A primary or metastatic malignant neoplasm involving the cervix. "Some studies have shown that TWIST1 is involved in cervical cancer progression by promoting cellular senescence." (PMID 41544137, 2026). "In SiHa and CaSki cervical cancer cell lines, 10 μM TQ has shown an ability to suppress the cancer metastasis, migration, and invasion by reducing Twist1 and Zeb1 expression and inducing E-cadherin expression in a dose- and time-dependent manner." (PMID 33923474, 2021). "In our cervical cancer cell lines SiHa, CaSki, and HeLa, low miR-9-5p expression coincided with high TWIST1 expression and vice versa." (PMID 31888045, 2019). "High CDH2 expression in cervical cancer cells coincided with low levels of miR-9-5p and high levels of TWIST1, suggesting a potential indirect effect of miR-9-5p on CDH2 via TWIST1." (PMID 31888045, 2019). "Based on our findings, we propose two different mechanisms for the involvement of miR-9-5p in the induction of EMT in cervical cancer: In SCC, abundance of miR-9-5p caused by a chromosomal gain of 1q leads to degradation of both TWIST1 and CDH1." (PMID 31888045, 2019). "MiR-9-5p mediated silencing of TWIST1 suggests two distinct mechanisms towards EMT in cervical cancer." (PMID 31888045, 2019). "Here we report for the first time the effectiveness of TQ in controlling cell growth and metastasis in cervical cancer cell lines via regulation of Twist1 and E-cadherin expression." (PMID 29207526, 2017). "We conclude that TQ inhibits the migration and invasion of cervical cancer cells, probably via Twist1/E-Cadherin/EMT or/and Zeb1/E-Cadherin/EMT, among other signaling pathways." (PMID 29207526, 2017). "Twist1/2 are basic helix-loop-helix transcription factors sharing 66% structural homology and repress E-cadherin expression in cervical cancer." (PMID 26356073, 2015). "Twist1 is a master regulator of EMT in cervical cancer and its expression is a poor prognostic factor." (PMID 26356073, 2015). "Recently, RNAi-mediated silencing of TWIST1 was shown to suppress the proliferation of human cervical cancer cells and to improve the chemosensitivity to cisplatin treatment, indicating a novel therapeutic strategy to overcome drug resistance." (PMID 23741524, 2013). "In the present study, our findings indicate a novel role of Twist1 in maintaining the cisplatin-resistant phenotype of cervical cancer HeLa cells through regulating MDR1/P-gp expression." (PMID 22245869, 2012). "Recently, a novel function of Twist1 was reported to confer radioresistance or chemoresistance in cervical cancer." (PMID 22245869, 2012). "In the present study, we firstly analyzed the relationship between Twist1 and MDR1/P-gp expression in human cervical cancer specimens and demonstrated a positive correlation between Twist1 and MDR1/P-gp expression in the same patient." (PMID 22245869, 2012). "Our results indicate a novel therapeutic strategy to overcome drug-resistance through inactivation of Twist1 expression in cervical cancer." (PMID 22245869, 2012). "Similarly, Twist1 and Zeb1 were downregulated by increasing promoter methylation in cervical cancer CaSki and SiHa cell lines." (PMID 33923474, 2021). "Twist1 promoter hypermethylation, one of the most important factors in the epigenetic reprogramming of Twist1, has been identified in cancers of different origins such as breast, bladder, gastric, colon and rectum, lung, ovary, and uterine cervix cancer." (PMID 28099910, 2017). "Targeting EMT-TFs like Twist1 and Zeb1 might be the possible mechanism of action of TQ in controlling metastasis in cervical cancer." (PMID 29207526, 2017). "Even if literatures support the hypothesis for a role of DNA methylation in the control of Twist1 expression, the differences treated with TQ are really too low in cervical cancer." (PMID 29207526, 2017).
cervical cancer (continued). "Thus, the results of our study linked to previous studies indicating that TQ inhibits the migration and invasion of cervical cancer cells probably via Twist1/E-Cadherin/EMT or/and different Zeb1/E-Cadherin/EMT signaling pathways." (PMID 29207526, 2017). "In cervical cancers, in comparison to TWIST1, TWIST2 may better stratify patients into prognostic subgroups and is shown to induce EMT and cell motility in cell lines." (PMID 25528769, 2015). "Supporting the idea that MEOX2 and TWIST1 contribute to oncologic treatment resistance, functional studies have shown that shRNA-mediated TWIST1 silencing in cisplatinum-treated cervical cancer cells regulates the expression of the multi-drug resistance receptor, MDR1/P-gp, also known as ABCB1." (PMID 25460568, 2014). "In addition, overexpression of Twist1 confers radioresistance or chemoresistance of cervical cancers, thereby leading to a poorer prognosis." (PMID 22245869, 2012). "Therefore, targeting Twist1 could be a novel therapeutic approach for the treatment of cervical cancer by overcoming drug resistance." (PMID 22245869, 2012). "Additionally, we provide the first evidence that silencing of Twist1 by RNAi downregulated MDR1/P-gp expression in HeLa cervical cancer cells, suppressed the cell proliferation, inhibited Rhodamine123 efflux activity of cells and sensitized cells to cisplatin treatment." (PMID 22245869, 2012). "Our study provided new evidence that HSP90 promotes EMT through increasing the expression of Twist1 and MCL-1, which were demonstrated to accelerate the process of EMT and invasion of cervical cancer cells." (PMID 32151082, 2020). "We show that STS-induced Twist1 expression is mediated in a HIF-1α–dependent manner in human prostate and cervical cancer cells." (PMID 28977889, 2017). "In this study, we firstly analyzed the relationship between Twist1 and MDR1/P-gp expression in cervical cancer specimens and demonstrated a positive correlation between Twist1 and MDR1/P-gp expression in the same patient." (PMID 22245869, 2012). "demonstrate that STC1-dependent immune escape from macrophage phagocytosis can be suppressed by the inhibition of competitive interaction between LNMAS and HMGB1, resulting in the abrogation of TWIST1 and STC1 chromatin accessibility, thereby suppressing cervical cancer lymph node metastasis." (PMID 38144565, 2023). "This active repression may be required to block TWIST1 expression, as STAT3 is activated by HPV in cervical cancer cells, and active STAT3 is an activator of TWIST1 expression, promoting EMT." (PMID 33298572, 2020). "To investigate whether the direct interaction between miR-9-5p and TWIST1 can (partly) explain the different role of miR-9-5p in cervical SCC and AC, we analyzed expression of CDH1 and CDH2 in cervical cancer cells." (PMID 31888045, 2019). "Additionally, we provided the first evidence that silencing of Twist1 downregulated MDR1/P-gp expression, inhibited its efflux activity, and sensitized cervical cancer cells to cisplatin treatment." (PMID 22245869, 2012). "Therefore, the purpose of this study was to investigate the relationship of Twist1 and MDR1/P-gp in cervical cancer and to explore whether Twist1 played an important role in drug resistance of cervical cancer cells by regulating MDR1/P-gp." (PMID 22245869, 2012). "However, the reason that Twist1 contributes to drug resistance in the treatment of cervical cancer has not yet been established." (PMID 22245869, 2012). "It is worth noting that a study conducted by Jiateng Zhong (2013), suggests that IKKβ (not identified by our searches) could phosphorylate Twist1 at multiple sites within the first 30 amino acids of Twist1’s N-terminus to trigger Twist destruction by β-TRCP in HeLa cervical cancer cells." (PMID 27556926, 2016).
non-small cell lung carcinoma (29 papers, 2012 to 2025). A group of at least three distinct histological types of lung cancer, including non-small cell squamous cell carcinoma, adenocarcinoma, and large cell carcinoma. "Furthermore, overexpression of Twist1 or N-cadherin in primary non-small cell lung cancers was associated with a shorter overall survival (P<0.01, P<0.01, respectively)." (PMID 23626784, 2013). "As a ceRNA, LINC01296 promotes tumorigenesis by regulating miR-598/Twist1 in non-small cell lung cancer (NSCLC) cells." (PMID 39901673, 2025). "Harmine is a beta-carboline alkaloid found in a variety of plants and was recently shown to be able to induce degradation of Twist Family BHLH Transcription Factor 1 (Twist1) in non-small cell lung cancer cells (NSCLC)." (PMID 33626096, 2021). "Twist1 is a candidate target for non-small cell lung cancer therapy, and development of small molecule inhibitors of Twist1 is an area of great interest." (PMID 31505764, 2019). "A recent investigation showed that PRMT1 regulated EMT by methylating Twist1 at the arginine residue 34, which is required for E-cadherin repression in non-small cell lung cancer cells." (PMID 26813495, 2016). "We also analyzed Twist1 and N-cadherin mRNA expression in 30 non-small cell lung cancer tissues using quantitative reverse transcription polymerase chain reaction." (PMID 23626784, 2013). "We extended these results in two other human non-small cell lung cancer cell lines, H727 and A549, showing that TWIST1 knockdown resulted in decreased proliferation and increased expression of markers consistent with activation of senescence." (PMID 22654667, 2012). "Twist1 overexpression corresponds with poor survival in non-small cell lung cancer (NSCLC), but the underlining mechanism is not clear." (PMID 26360779, 2015). "For example, EMT-TFs such as TWIST1 and ZEB1 have been reported to drive EMT-mediated resistance to EGFR inhibitors in EGFR-mutant non-small cell lung cancer." (PMID 36781842, 2023). "Notably, exosomes from HPV-16 E7-expressing non-small cell lung cancer (NSCLC) cells dramatically promoted EMT, evidenced by the upregulation of mesenchymal markers (Vimentin, N-cadherin, Snail1, Slug, Twist1) and suppression of E-cadherin." (PMID 41154440, 2025). "“Linear programmed necrosis” in non-small cell lung cancer induces tumor cells to die linearly and provides space for VM formation; second, it promotes the expression of MMP2, Twist1 and Slug, promoting extracellular matrix remodeling and EMT by DKK1, which in turn promotes VM formation." (PMID 37217473, 2023). "In non-small cell lung cancer (NSCLC), the inhibition of proliferation mediated by SIRT6 is the result of the suppression of Twist1 expression, a key player involved in two different tumor processes such as metastatization and epithelial-mesenchymal transition (EMT)." (PMID 33800266, 2021). "TWIST1 and CRIPTO1 co-expression was correlated with larger tumor size, advanced stages of tumor progression, poorly differentiated state of tumors, presence of distant metastases, poor 3-year survival rates, and disease progression in non-small cell lung carcinoma." (PMID 36553636, 2022).
triple-negative breast carcinoma (29 papers, 2014 to 2025). An invasive breast carcinoma which is negative for expression of estrogen receptor (ER), progesterone receptor (PR), and human epidermal growth factor receptor 2 (HER2). "Low dox concentrations have been implicated in favoring the metastatic process of triple-negative breast cancer cells through activation of TGF-β1 and upregulation of the RhoA/MLC or Twist1 pathway." (PMID 39056658, 2024). "Twist1 expression induced by sunitinib accelerates vasculogenic mimicry and induction of cancer stem cell marker in triple negative breast cancer (TNBC) cells." (PMID 31138781, 2019). "Taken together, these data suggests that SOX2 and TWIST1 are major regulators of CSC features in human triple negative breast cancers." (PMID 28835684, 2017). "Dendrimers carrying siRNA against TWIST1 reduced migration in vitro and homed to tumors in a xenograft model of triple negative breast cancer in mice." (PMID 28283022, 2017). "Silencing MUC1-C could inhibit Twist1 and thereby reverses the paclitaxel resistance in triple-negative breast cancer." (PMID 36781842, 2023). "In this study, we show that SNAI2, a mediator of EMT highly expressed in triple-negative breast cancer, is upregulated in endocrine-resistant cells, whereas other EMT-associated transcription factors, such as SNAI1/3, TWIST1/2, ZEB1/2, FOXC2, and GSC, are unaltered." (PMID 29921289, 2018). "ANLN is also upregulated in triple-negative breast cancer(TNBC), where it enhances cancer stemness and promotes sphere formation via the TWIST1 and BMP2 signaling pathways." (PMID 41573677, 2025). "α-Linolenic acid inhibits the migration of human triple-negative breast cancer by attenuating the phosphorylation of c-Jun N-terminal kinase (JNK), ERK, and Akt, reducing TWIST1 expression, and inhibiting TWIST1-mediated EMT." (PMID 40821113, 2025). "And digestive tumor research can reference its mechanisms elsewhere, e.g., metastasis inhibition via circNAV3/miR-4262/ST6GALNAC5/EGFR (as in triple-negative breast cancer) or progression suppression through m6A/IGF2BP3-stabilized TWIST1 mRNA." (PMID 40978472, 2025). "In triple-negative breast cancer, USP29 was recently reported to be phosphorated and activated by cyclin-dependent kinase 1 (CDK1), and then deubiquitinate and stabilize twist family bHLH transcription factor 1 (TWIST1), which is a key regulator of epithelial-mesenchymal transition." (PMID 38233848, 2024). "Furthermore, MUC1-C binds to Twist1 and forms an autoregulatory loop with Twist1, regulating EMT and acquired paclitaxel resistance in triple-negative breast cancer." (PMID 36781842, 2023).